NPC1 (NPC intracellular cholesterol transporter 1)
Diseases named in the same sentence as NPC1 in open-access papers (continued):
Sharing a sentence is not in itself a finding about the gene and the disease.
Ataxia (40 papers, 2009 to 2025). Ataxia refers to impaired coordination of voluntary muscle movement. "A murine model of Npc1−/− displays a rapidly progressing form of Npc1 disease, which is characterized by weight loss, ataxia, and increased cholesterol storage." (PMID 39081805, 2024). "Phenotypically, loss of NPC1 in oligodendrocytes contributes to motor deficits and ataxia, and even triggers the loss of Purkinje neurons." (PMID 38368932, 2024). "CALB1 is of particular interest in NPC1 since it is highly expressed in cerebellar Purkinje neurons, the loss of which underlie the cerebellar ataxia which is a predominant symptom in NPC1." (PMID 36721240, 2023). "The patient’s overlapping clinical synopsis of hepatosplenomegaly, ataxia, developmental regression, and interstitial lung disease can be explained by the context of this variant in NPC1." (PMID 35741735, 2022). "The context of the variant in NPC1 explains the patient’s overlapping clinical description of hepatosplenomegaly, ataxia, developmental regression, and interstitial lung disease." (PMID 35741735, 2022). "Similar to the NPC1 disease heterogeneity, there are potentially many underpinnings contributing to the swallowing dysfunction: cerebellar ataxia, cranial nerve dysfunction causing oral-motor weakness, and dyscoordination of swallowing and respiratory cycles." (PMID 36064725, 2022). "We identified changes in the intrinsically generated firing patterns in NPC1-deficient adult mice affected by ataxia and changes in the synaptic modulation of cPCs prior to the onset of ataxia." (PMID 33445799, 2021). "These neurons are of particular interest because progressive rostral to caudal loss of Purkinje neurons is a pathological hallmark of NPC1, and loss of Purkinje neurons results in cerebellar ataxia, a major clinical feature of NPC1." (PMID 32731618, 2020). "We focused on the cerebellum given that Purkinje neuron loss is a major pathological finding in NPC1, and the resulting cerebellar ataxia is a cardinal symptom in this disorder." (PMID 32731618, 2020). "Purkinje neuron loss and resulting cerebellar ataxia are cardinal features of NPC1, thus we were particularly interested in determining transcriptomic changes in NPC1 mutant Purkinje neurons." (PMID 32731618, 2020). "NPC1-patients suffer from, amongst other symptoms, ataxia, based on the dysfunction and loss of cerebellar Purkinje cells." (PMID 31847086, 2019). "Ataxia, a pathological hallmark of NPC1, is caused by dysfunction and progressive loss of Purkinje cells, displaying the sole output of the cerebellar cortex." (PMID 31847086, 2019). "NPC1-patients suffer, amongst others, from ataxia, based on a loss of cerebellar Purkinje cells (PCs)." (PMID 29463856, 2018). "This causes NPC1 patients to develop a progressive form of ataxia in adolescence and adulthood." (PMID 40654857, 2025). "NPC1 is an AR disorder caused by biallelic pathogenic variants in the NPC1 gene, typically presenting in infancy or childhood with symptoms such as hepatosplenomegaly, failure to thrive, hypotonia, ataxia, dysphagia, and intellectual disability." (PMID 39161410, 2024). "A cardinal symptom of NPC1 is cerebellar ataxia due to Purkinje neuron loss." (PMID 32731618, 2020). "Cerebellar ataxia in NPC1 results from the progressive loss of cerebellar Purkinje neurons." (PMID 32731618, 2020). "In Npc1 knockout mice, STING signaling was upregulated and mice were characterized by Purkinje cell (PC) loss and ataxia motor phenotype, while genetic deletion of Sting1 improved PC abundance and ataxia scores." (PMID 39156128, 2024). "All patients were tested with whole genome sequencing containing hereditary ataxia panels, which include NPC1 and NPC2 mutations and other genetic causes of ataxia." (PMID 38790666, 2024).
Ataxia (continued). "Research has shown that a higher proportion of patients with early-onset cerebellar atrophy and ataxia carry variants in SNX14 (9.88%) compared to other known pathogenic genes such as GRID2 (2.47%), NPC1 (1.23%), and SETX (1.23%)." (PMID 38655056, 2024). "In a large cohort of adults with ataxia, plasma 3β,5α,6β-triOH-Gly was able to detect the one patient in the cohort with NPC1 disease, but also detected oxidation of cholesterol by ROS in other disorders." (PMID 38790666, 2024). "Npc1−/− mice initially display a pre-symptomatic phase, followed by mild cerebellar ataxia and tremor at the age of six weeks, which become more prominent at eight weeks of age." (PMID 38368932, 2024). "In the mouse model of NPC (Npc1–/– mice) hypomyelination is pronounced in the cerebral cortex and the CC, presumably accounting for the tremor and ataxia observed in these animals." (PMID 38163061, 2023). "As a result, the female NPC1 mice that received CD4-positive T lymphocytes exhibited an improvement of cerebellar ataxia." (PMID 37369603, 2023). "The ataxia observed in NPC1 patients is based on the selective death of cerebellar Purkinje cells (cPCs)." (PMID 33445799, 2021). "Here, we investigated acetyl-dl-leucine and its enantiomers acetyl-l-leucine and acetyl-d-leucine in symptomatic Npc1−/− mice and observed improvement in ataxia with both individual enantiomers and acetyl-dl-leucine." (PMID 33738443, 2021). "We found that ADLL, ALL and ADL significantly improved ataxia when symptomatic Npc1−/− mice were treated acutely for 7 days; this is in agreement with observational studies in NPC1 patients treated with ADLL, using the same dosage per kg and day." (PMID 33738443, 2021). "ADLL therapy in NPC1 patients led to significant improvements in cerebellar ataxia as well as in cognition and behaviour, suggestive of potential functional benefits beyond the cerebellum." (PMID 33738443, 2021). "NPC1 patients also displayed developmental regression, “frequent falls and ataxia”, spasticity, dysphagia, and nystagmus as an initial neurological symptom." (PMID 32709131, 2020). "One of the phenotypic hallmarks of Npc1 mouse models is progressive motor impairment, which manifests as ataxia and changes in gait." (PMID 31996359, 2020). "In a study of 96 patients with unexplained EOA (age at onset < 40 years), targeted high-throughput sequencing of 122 known ataxia genes including NPC1 and NPC2, NP-C diagnoses were confirmed in 2/96 patients (2.1%)." (PMID 30665446, 2019). "NPC1 patients develop severe neurological-neurovisceral disorders, including cerebellar ataxia, dysarthria, dysphagia, seizures, and progressive dementia." (PMID 31178699, 2019). "Previous reports have described ectopic expression of Th within the Purkinje neurons of various murine models of cerebellar ataxia, including tottering, leaner, pogo, rolling Nagoya, dilute-lethal, and Npc1−/− mice." (PMID 31906248, 2019). "Alterations of PC morphology and localization are responsible for ciliopathies, disorders that manifest, like the NPC1 disease, a constellation of clinical features including ataxia, retinal degeneration, behavioral disturbance, and intellectual disability." (PMID 31178699, 2019). "A hampered function and/or loss of cerebellar glutamate transporters play a crucial role in the pathology of e.g. spinocerebellar ataxias, suggesting a contribution to the ataxia observed in NPC1." (PMID 29463856, 2018). "Clinically manifested, CB involved tremor and ataxia comprise one of the hallmarks of NPC1 disease in both humans and animal models." (PMID 30429460, 2018). "The NPC1 phenotype is characterized by progressive neuronal dysfunction, including cerebellar ataxia and dementia." (PMID 26986514, 2016). "Pathological features in NPC1−/− mice resemble those observed in late infantile NPC1 disease in humans, exhibiting progressive neurodegeneration, hepatosplenomegaly and ataxia." (PMID 22163015, 2011).
Ataxia (continued). "Behaviorally, onset of ataxia in untreated Npc1−/− mice occurred between 6 and 7 weeks of age, while CD treatment delayed onset by 3 weeks, such that treated Npc1−/− mice became ataxic between 9 and 10 weeks of age." (PMID 19750228, 2009). "Our study showed that some adults with ataxia who were shown to have no mutations in NPC1 or NPC2, had high plasma concentrations of 3β,5α,6β-triOH-Gly." (PMID 38790666, 2024). "The rotarod test revealed an enhanced cerebellar ataxia in both female and male NPC1 mice." (PMID 37369603, 2023). "In addition, a recent report has identified compound heterozygous mutations in NPC1 in a patient diagnosed with Pelizaeus–Merzbacher-like disease (PMLD), a hypomyelination defect resulting in ataxia and progressive motor dysfunction, among other symptoms." (PMID 35563467, 2022). "We observed the loss of Purkinje cells in the cerebella of the NPC1−/− homozygous fish and the aberrant motor behaviour, i.e., ataxias, a typical pathological character of human NPC1 patients (unpublished data), indicating its potential value for investigating the molecular mechanisms of NPC1." (PMID 34639106, 2021). "NPC1 patients suffer from various neurological symptoms, such as ataxia." (PMID 33445799, 2021). "Consistent with the key role of NPC1 in intracellular cholesterol trafficking, NPC1 deficiency in mice reproduces many of the deficits seen in NPC patients, including neurological defects and ataxia by 6–7 weeks of age and severe reduction in the maximal life span to about 10–12 weeks." (PMID 29249985, 2017). "Moreover, npc1 mutants had a reduced body length and exhibited ataxia symptoms." (PMID 33917666, 2021). "In contrast, the study from Tubingen, Germany, identifying patients by sequencing NPC1 and NPC2 detected six cases in 204 individuals with early-onset ataxia." (PMID 38790666, 2024). "NPC1 and NPC2 are currently included in gene panels for infantile cholestatic disease, early onset ataxia (EOA), dystonia, IEMs, organic psychosis, early-onset cognitive decline, hepatosplenomegaly, and developmental delay." (PMID 30665446, 2019). "Despite normal c-triol concentrations, a genetic analysis of NPC1 or NPC2 was performed, as these patients presented typical clinical symptoms, including ataxia, dysarthria, vertical supranuclear gaze palsy, dysphagia and psychosis." (PMID 26981555, 2016). "Most NPC cases are due to loss of function of NPC1, and consequently, mice with NPC1 deletion (Npc1−/− knockout mice) reproduces many of the deficits seen in NPC patients, including the neurological symptoms, ataxia by 6–7 weeks of age, and reduced maximal life span to about 10–12 weeks." (PMID 31787922, 2019).
Obesity (34 papers, 2010 to 2025). Accumulation of substantial excess body fat. "Various genetic studies have implicated NPC1 in its susceptibility to obesity, and it is associated with early-onset and morbid adult obesity." (PMID 35207755, 2022). "A genome-wide association study identified a single-nucleotide polymorphism (SNP) in NPC1 associated with obesity, and NPC1 haploinsufficiency in mice induces hepatosteatosis and features of metabolic syndrome." (PMID 33348067, 2021). "Young patients of the same population carrying heterozygous NPC1 LOF mutations had a fivefold increase in the risk of obesity, although only the associations in men reached significance when the results were stratified by sex14." (PMID 33139814, 2020). "Heterozygous carriers of partial/complete loss-of-function coding mutations in the NPC1 gene confer an increased risk of obesity in East Asian populations." (PMID 33139814, 2020). "This is the first study to investigate the prevalence of NPC1 mutations in diverse ethnic groups, providing a global understanding of the implications of NPC1 in obesity risk and NPC1 disease." (PMID 33139814, 2020). "It has been reported that rs1805081 (p.His215Arg) and rs1805082 (p.Ile858Val) polymorphisms of the NPC1 gene are associated with early-onset and morbid adult obesity in a European population and Chinese children." (PMID 30458724, 2018). "The UCP1 and NPC1 genes are known to be involved in the regulation of energy metabolism and the role of the polymorphisms in these genes with respect to obesity is arguable due to the diverse results of studies performed in different ethnicities." (PMID 30458724, 2018). "In European populations, a GWAS identified three new alleles of NPC1 strongly associated with obesity." (PMID 28913343, 2017). "In line with this strategy, we have previously identified that a gain-of-function variant in LGR4 and rare loss-of-function variants in NPC1 predispose to obesity." (PMID 28988979, 2017). "A convincing genome wide association study (GWAS; multiple populations, multiple polymorphisms, both genders; 11, 12, 13, 15, 16, 17, 18, 19) demonstrated a link between variation at the NPC1 locus and risk for obesity and diabetes." (PMID 28913343, 2017). "An early GWAS revealed that the Niemann-Pick C1 gene (NPC1) is associated with morbid-adult obesity (≥ 40kg/m2) in an European population." (PMID 26120596, 2015). "The physiological mechanisms describing how NPC1 loss-of-function mutations or polymorphisms predispose to either NPC1 disease or common metabolic diseases (obesity and diabetes) remain undefined." (PMID 26120596, 2015). "SNPs within NPC1 have been associated with obesity and type 2 diabetes, and mice heterozygous or null for NPC1 are insulin resistant." (PMID 24752197, 2014). "Single nucleotide polymorphisms (SNPs) within the NPC1 gene have been associated with early onset and morbid obesity and, independently of obesity, insulin resistance in humans." (PMID 24752197, 2014). "SNPs in the FTO, GNPDA2, SEC16B, BDNF, TMEM18 and NPC1 loci associated with increased risk of both overweight and obesity." (PMID 23861046, 2013). "Conversely, the effect on obesity risk and higher BMI of the NPC1 SNP in Asian populations is still controversial." (PMID 23153210, 2012). "In line with this evidence, a nonsynonymous polymorphism (rs1805081, His215Arg) in the human NPC1 gene has recently been associated with severe and early onset obesity in European populations." (PMID 23153210, 2012). "As well as identifying variants in FTO and MC4R, they detected a further three loci associated with obesity (NPC1, MAF and PTER)." (PMID 21935397, 2011). "In humans, GWAS showed common NPC1 variants associated with obesity." (PMID 32982666, 2020). "As for carriers of NPC1 disease, it is possible that this variant is only partially deleterious and thereby placing patients at increased risk of less penetrant disease manifestations such as obesity." (PMID 33139814, 2020).
Obesity (continued). "Depending on the ethnic group, between 0.56% and 3.26% of the gnomAD population is heterozygous for NPC1 pathogenic mutations that may result in a high-risk of obesity." (PMID 33139814, 2020). "We hypothesize a pivotal role of the NP-C pathway, particularly the NPC1 protein, as a nexus in lysosomal lipid metabolism that prevents the lipid toxicity that underlies many metabolic disturbances such as obesity and diabetes." (PMID 28913343, 2017). "Genetic studies have implicated the NPC1 gene (Niemann Pick type C1) in susceptibility to obesity." (PMID 23360456, 2013). "NPC1 may partially influence susceptibility to obesity by altering adipocyte function although further studies are needed to decipher its contribution to obesity development." (PMID 23360456, 2013). "Association analysis of NPC1 polymorphisms with obesity, BMI, and T2D." (PMID 23153210, 2012). "A polymorphism (His215Arg) in NPC1 was associated with obesity in Europeans." (PMID 23153210, 2012). "Furthormore, rs1805081 has been found to be associated with obesity and Alzheimer's while studies in mice suggest that the G allele is protective here and might be associated with NPC1 activity." (PMID 20955564, 2010). "In addition, PAS-SNPs have also been identified in other obesity-related genes: Abcc6 and Npc1 in the Fat line and Lsamp (limbic system-associated membrane protein) in the Lean line, as well as in Arhgap8 (Rho GTPase activating protein 8) in the Fat line, which is localised in the dominant Fob2." (PMID 36414820, 2023). "Similarly, NPC1 has been shown to be associated with obesity." (PMID 35480314, 2022). "Therefore, NPC1 heterozygous mutations may account for a substantial and ethnic-dependent percentage of obesity in the general population, while NPC1 homozygous mutations may be frequent in the South Asian populations and warrants more investigation." (PMID 33139814, 2020). "Interestingly, NP-C disease, while itself a true orphan disorder, typifies the advantages of a studying rare diseases caused by unimolecular causation; variation in the NPC1 protein is associated with obesity risk and susceptibility to a variety of viral infections." (PMID 28913343, 2017). "GWAS of SevO found numerous susceptibility loci that intersected with earlier-identified BMI loci including the archetypal FTO, MC4R, SH2B1 and NPC1 suggesting little etiological heterogeneity between obesity subgroups." (PMID 40939575, 2025). "Because of the involvement of NPC1 in obesity, this gene can be considered in the differential diagnosis of lipedema." (PMID 35207755, 2022). "Our results also revealed that the genotype of rs150703258 was associated with BMI, indicating the genetic contributing roles of NPC1 to obesity." (PMID 35480314, 2022). "A recent study performed in humans with obesity reported that NPC1 expression was significantly higher in the subcutaneous and omental white adipose tissue, and it was lower after weight loss." (PMID 35207755, 2022). "There are several genetic mutations in the NPC1 gene associated with cardiovascular disease (CVD), CHD, overweight, obesity and morbid obesity." (PMID 35480314, 2022). "The genes reviewed here are FTO, NRXN3, NPC1, NEGR1, MTCH2, and GNPDA2, which were chosen for their association with obesity and their influence on NDgD or NDvD." (PMID 32982666, 2020). "The prevalence of NPC1 heterozygous carriers in our study is consistent with previously reported prevalence of obesity across different ethnic groups." (PMID 33139814, 2020). "Other studies also observed a latent weight gain in NPC1+/− mice fed a HFD22–25, supporting the adult onset of obesity observed in human NPC1 variant carriers." (PMID 33139814, 2020). "The Niemann-Pick C1 gene (NPC1), another reported genetic determinant of obesity, is a gene for transmembrane glycoprotein located in the limiting membrane of late endosome/lysosome (LE/LY) and mediates intracellular trafficking of sterols." (PMID 30458724, 2018).